NOS2 (nitric oxide synthase 2)
Diseases named in the same sentence as NOS2 in open-access papers (continued):
Sharing a sentence is not in itself a finding about the gene and the disease.
infection (continued). "The infection of murine in vitro generated Hoxb8 neutrophils with A. phagocytophilum induced the expression of inducible or type 2 nitric oxide synthase (iNOS or NOS2) mRNA and the secretion of significant amounts of MIP-1α (CCL3), RANTES (CCL5), and TNF." (PMID 33747981, 2021). "At day 4 post infection, there were significant increases in the frequencies of cells positive for NOS2 and/or IFN-γ, among the CD11b+ and NK populations, respectively, in mice infected with TbISP2-null mutants." (PMID 34153047, 2021). "It was described that IDO1 and NOS2 are co-expressed as a result of infection or inflammation in human tissues." (PMID 33807310, 2021). "During L. major infection in vivo, HIF-1α and HIF-2α, as well as multiple HIF-1α and HIF-2α targets, including Vegfa, Nos2, and Arg1, are elevated at the site of infection." (PMID 34959539, 2021). "There has been some evidence that higher NOS2 activity in humans correlates with protective immunity to infections." (PMID 34777283, 2021). "NO is produced from L-arginine by three NO synthases (NOS1, NOS2 and NOS3) and NOS2 is responsible for high level of NO production under pathophysiological conditions such as an infection." (PMID 32459575, 2020). "Except during the very early phase at day 14 after infection, the gene expression of Nos2 and Lrg47 was significantly reduced in lung homogenates of CD4cre; gp130loxP/loxP mice during the further course of infection." (PMID 33375150, 2020). "In order to analyze macrophage activation in the course of granuloma formation after infection with Mtb, NOS2 was examined immunohistochemically in lung tissue sections of infected mice." (PMID 33375150, 2020). "In the present study, four host genes (Gm15587, Nos2, Pycr1, Arg2) were enriched in this metabolic pathway, two of which (Nos2, Pycr1) were downregulated in the infection group." (PMID 32509459, 2020). "The Irf1 and Stat1 contribute to the control of T. gondii by regulating the expression of factors essential for the host to resist infection, such as Socs1, Ciita, and NOS2." (PMID 33193165, 2020). "Researchers findings using Campylobacter jejuni in an experimental infection agree with the beneficial effect of blocking NOS2 with AG." (PMID 33091049, 2020). "These analyses demonstrated that 4 immune genes including CATH-1, IL-10, heat shock proteins, and NOS2 were all significantly upregulated in the OO during early infection." (PMID 33304348, 2020). "In agreement, the appearance of NOS2 expressing cells coincided with the formation of clearly defined granuloma containing epithelioid macrophages at 3 weeks of infection." (PMID 32408806, 2020). "Compared to WT animals, lungs of Il22−/− mice exhibited reduced gene and protein expression of NOS2 at 7 and 14 days after infection (respectively)." (PMID 32517114, 2020). "This suggests that NOS2 is being regulated at the post-translational or enzymatic level during AF2122/97 infection." (PMID 31527895, 2019). "The comparative analysis of the expressed values for IL-1β and NOS2 were statistically different between the assays, compared to the attenuated and virulent strains, differing when compared to the control groups and infection with the saprophytic strain." (PMID 31800570, 2019). "Our laboratory has previously shown that ARG1+, NOS2+ macrophages accumulate in the duodenal lamina propria following infection and resemble myeloid-derived suppressor cells." (PMID 31455692, 2019). "We show that F4/80+, CD11b+, CD11cint, CX3CR1+, MHC class II+, Ly6C−, ARG1+, and NOS2+ macrophages accumulate in the small intestine during infections in mice." (PMID 31455692, 2019). "Our previous studies showed that these miRNAs reduce Nos2 expression and NO production, enabling the establishment of infection." (PMID 30949455, 2019). "In contrast, NOS2 is widely distributed in multiple cell types, and is significantly induced under certain infection or inflammatory stimulations via PAMPs." (PMID 31766159, 2019).
infection (continued). "Our data revealed that melatonin treatment of macrophages promoted modulation of the expression of mRNA involved in L-arginine metabolism during infection, inducing Nos2 to the detriment of Arg1 and thus altering infectivity." (PMID 30949455, 2019). "Knocking-down NOS2 reduced the nitrite levels in the supernatants 48 hpi by 93% with AF2122/97 infection." (PMID 31527895, 2019). "We have previously reported that ARG1, NOS2 dual expressing macrophages accumulate in the intestine following infection with Giardia and used these markers to assess accumulation in this experiment." (PMID 31455692, 2019). "In contrast, our work showed that melatonin treatment of BALB/c BMDMs increased Nos2 mRNA expression and NO production during infection, leading to a decreased infection index." (PMID 30949455, 2019). "Still, melatonin sustained the levels of Nos2 mRNA and increased the frequency of NO-producing cells and the amount of NO per cell at 24 h of infection." (PMID 30949455, 2019). "The cytokines IL-12 and IL-4 induce CAT2B expression and the uptake of L-arginine, a substrate of ARG1 and NOS2, altering outcome of infection, while the negative regulation of CAT2B expression also reduces the infectivity of L. amazonensis." (PMID 30555476, 2018). "In contrast, MyD88−/− macrophages showed decreased levels of Arg1 and Nos2 transcripts in all infection periods analyzed (respectively)." (PMID 30555476, 2018). "The level of the Nos2 transcript was reduced following let-7e inhibition 4 h after infection, but Nos2 levels were increased 24 h after infection." (PMID 30555476, 2018). "The only transcript whose expression was modulated during the course of infection was Nos2, which was increased at 24 h and decreased at 48 h after infection." (PMID 30555476, 2018). "NOS2, which also generates reactive oxygen species to fight pathogens, was upregulated during infection." (PMID 30778359, 2018). "The comparison between WT and TLR4−/− macrophages revealed decreased levels of the Arg1 and Nos2 transcripts throughout the course of infection (respectively)." (PMID 30555476, 2018). "Earlier studies of Salmonella pathogenesis have demonstrated definite upregulation of NOS2 expression in response to infection." (PMID 30452468, 2018). "The comparison between WT and TLR2−/− macrophages showed increased levels of the Arg1 transcript 4 h after infection and decreased levels of Nos2 transcript in all infection periods analyzed (respectively)." (PMID 30555476, 2018). "We found increased gene expression of Nos2 and Nitrite in Stat2−/− mice compared to WT with super-infection." (PMID 30337919, 2018). "We show that M. tuberculosis-infected HSPCs in bone marrow are involved in propagating systemic hallmarks of the primary infection after adoptive cell transfer to naive mice, contingent on the inability of these cells to express NOS2." (PMID 29471332, 2018). "In contrast, Nos2−/− mice showed a steady decline in weight from 2 weeks post-infection, and required termination of the experiment 23 days post-infection at a pre-specified humane endpoint." (PMID 30573728, 2018). "In these conditions, Nos2 mRNA was not significantly modified after 4 and 24 h of infection, but NOS2 expression and NO production were increased parallel to a decreased infectivity after 4 and 24 h of infection." (PMID 28276497, 2017). "Classical macrophage activation plays a central role in combating infection with Mtb through IFN-γ-induced expression of effector molecules such as the NOS2-dependent production of RNI." (PMID 29176982, 2017). "The authors concluded that in this infection model, canine macrophages were able to express NOS2 and that IFN-γ and LPS have a role in NOS2 production." (PMID 27094260, 2017). "The lack of arginase in L. (L.)amazonensis led to a similar up-regulation of the host Nos2 and Cat1 mRNAs, but Cat2B expression was reduced after 4 h of infection in comparison to uninfected macrophages." (PMID 28276497, 2017).
infection (continued). "Because in Mtb-infected LysMcreSOCS3loxP/loxP mice an elevated arginase activity precedes the increased induction of NOS2 mycobacteria were mostly found in Arg1-expressing cells at early time points of infection." (PMID 29176982, 2017). "The infection of macrophages with arginase addback promotes a similar phenotype of La-WT, inducing high levels of miR-294-3p and miR-721 and low levels of Nos2 mRNA, NOS2 and NO production." (PMID 28276497, 2017). "Yet, after infection with Mtb the expression of Nos2 and the production of RNI were rather elevated in the absence of macrophage SOCS3." (PMID 29176982, 2017). "In lungs of LysMcreSOCS3loxP/loxP mice, 1 week after infection Arg1 precedes Nos2 gene expression and accordingly Arg1-positive cells were abundant, whereas NOS2-positive cells were hardly detectable." (PMID 29176982, 2017). "This early mucosal resistance phenotype was associated with an early increase of mucosal protein levels of IL-1β, IL-22, KC/CXCL1 and MCP-1 and elevated transcription rates of Cxcl1 and Nos2/iNos measured at 18 hours post infection." (PMID 28662171, 2017). "IFN-I blockade led to abolishment of NOS2 function and reduced cytotoxic activity and IFNγ production by NK cells at early stages of infection." (PMID 28154565, 2017). "The accumulation of Nos2 mRNA and NOS2 during La-arg− infection suggested that miR-294-3p and miR-721 act at a post-transcriptional level by degrading Nos2 mRNA." (PMID 28276497, 2017). "The pivotal use of L-arginine in the polyamine pathway or in NO production via NOS2 activation can determine the fate of the parasite during infection." (PMID 28276497, 2017). "Our study demonstrated for the first time the role of miR-294 and miR-721 in the regulation of Nos2 expression, which is dependent on Leishmania arginase and can determine the fate of infection favoring Leishmania survival or killing in the host." (PMID 28276497, 2017). "Meanwhile, parasites with no ARG activity reduce the expression of those miRNAs and increased NOS2 and NO production, leading to the control of the infection of BALB/c macrophages." (PMID 29379478, 2017). "The miScript Target Protector (Qiagen) competition assay for the binding site of miR-294 to the Nos2 3′UTR using 0.1 μM or 0.5 μM miR-294/Nos2 revealed a significant increase (20% to 22%) in the levels of NOS2 after 4 h of infection." (PMID 28276497, 2017). "The reduction in miR-294 expression did not promote a statistically significant change in the amount of Nos2 mRNA, even so NOS2 expression and NO production was increased after 4 and 24 h of infection, parallel to a 25–30% decrease in infectivity." (PMID 28276497, 2017). "For confirm the importance of La-arginase for Nos2 expression and its implications in the miR-294-3p and miR-721 expression during infection, we performed experiments with L. (L.)amazonensis arg− addback arginase (La-arg− + ARG)." (PMID 28276497, 2017). "NO production is not only increased in macrophages but NOS2 mRNA expression and the production of NO is increased in A549 lung epithelial cells following infection with Mtb bacilli." (PMID 29085351, 2017). "We next examined the contribution of each IFN pathway to the induction of Nos2 transcription upon in vivo infection with M. tuberculosis strain BTB 02-171." (PMID 27849167, 2016). "TLR4 activation by M. tuberculosis was found to result in the expression of host-protective factors (e.g., TNF, IFN-γ, and NOS2) and to limit bacterial growth during in vivo infection." (PMID 27849167, 2016). "Our findings demonstrate that type I IFN induces Nos2 and inhibits Arg1 expression following infection of macrophages with M. tuberculosis, resulting in high NO production by infected macrophages." (PMID 27849167, 2016). "At the beginning of the chronic phase (29 days post-infection), we observed a strong decrease of Ifng, Il6, Gzmb concomitant with and an increase of Nos2, Ptgs2 mRNA levels." (PMID 28018318, 2016).
infection (continued). "Nos2 expression, indicative of M1 type macrophage polarization, was foundup-regulated in WT mice early upon infection whereas it was down-regulated inp40−/− mice." (PMID 27001522, 2016). "At 29 days post-infection, Ifng, Gzmb, and Il6 mRNA levels strongly decreased whereas a strong up-regulation of Ptgs2 and in a lesser extent Nos2 and Ccl2 mRNA levels remained." (PMID 28018318, 2016). "The qPCR results revealed that the well-known Mtb-activated genes Tnf, Csf3, Nos2 and Il10 were upregulated at 6 h and 24 h post-infection, and the fold changes at 24 h were higher than at 6 h." (PMID 26912204, 2016). "NOS2-generated nitric oxide is required for efficient L. monocytogenes cell-to-cell spread during infection, although this is due to the nitric oxide-mediated delay of phagolysosome maturation and not a direct effect on the bacteria." (PMID 27414028, 2016). "In this study, we provide evidence that DENV/DENV-ADE infection of monocytes induces early production of ISG (NOS2) through the RIG-I/MDA-5-MAVS-NF-κB/IRF-1 signalling axis independent of the IFN pathway." (PMID 26923481, 2016). "Meanwhile, both DENV and DENV-ADE infection induced direct expression of NOS2 through activation of the RIG-I/MDA-5-MAVS signalling axis." (PMID 26923481, 2016). "For that, we injected intravenously C57BL/6 mice with stationary promastigotes of each L. infantum strain and analyzed the liver expression of Nos2 and Arg1 as well as of Tnf, Ifng, Il-12p40 and Il-10 genes, 15 and 60 days after infection." (PMID 26684322, 2015). "In contrast, a subsequent study showed that these antimicrobial mechanisms had no influence on the outcome of L.donovani infection in the liver, though NOS2 exerted moderate protective effects in the spleen at late phases of infection." (PMID 26684322, 2015). "A first report by Murray and Nathan in 1999 demonstrated that both NADPH oxidase and NOS2 were involved in the early control of L. donovani replication in the liver, whereas NOS2 alone was sufficient to resolve late infection." (PMID 26684322, 2015). "Mouse experimental infections with Leishmania contributed decisively to identify phagocyte oxidase (phox) and especially nitric oxide synthase 2 (NOS2) as fundamental antimicrobial weapons of the macrophage." (PMID 26684322, 2015). "Consistently with the cytometry and the immunofluorescence data, the transcription of Ifnγ, Il17, Tnf and Nos2 was similar in both groups at day 30 post-infection." (PMID 26135889, 2015). "Further confirmatory experiments were performed using APECs from C57BL/6 and Nos2-/- mice that were infected with S. Typhimurium and their internalization, i.e entry into cells, was monitored after 2 h post infection." (PMID 26029930, 2015). "Overall, our studies provide novel mechanistic insights into the roles of Nos2 in mediating morphology, motility and aggregation behavior of APECs upon Ifnγ stimulation and in response to infection with S. Typhimurium." (PMID 26029930, 2015). "Between 73 and 89 days after infection with Mtb, NOS2 was expressed throughout the granulomas in both wild-type and IL-13tg mice, with the exception of necrotic granuloma centres." (PMID 24979482, 2014). "During the course of infection, infg and nos2 gene expression were only reduced in lungs from IL-13tg mice at 21 days of infection." (PMID 24979482, 2014). "In contrast to C57BL/6, flow cytometric analysis clearly identified two CD11b+ populations in the lungs of M. tuberculosis infected NOS2 -/- mice after 30 days of infection." (PMID 24224058, 2013). "Down-regulation by 2–4 fold of genes encoding immune mediators such as IFN-γ, IL-1B, IL-1m, lactoferrin (Ltf) and nitrous oxide synthase 2 (Nos2) was consistently observed at 5 and 9 days post-infection." (PMID 23861742, 2013). "These Nos2-deficient animals exhibited fewer histopathological alterations following infection, confirming the importance of NOS2 in the neuropathogenesis of neurovirulent DENV." (PMID 23978258, 2013).
infection (continued). "Mice in which genes have been deleted for gamma interferon, B and T cells, GM-CSF, and NOS2 all develop severe lung necrosis after low dose aerosol infection." (PMID 24224058, 2013). "Four WT infected mice per group were euthanized each day for eight days after infection and analyzed to verify the expression levels of virus genes, cytokines and Nos2 transcripts by real-time PCR." (PMID 23978258, 2013). "Production of reactive nitrogen intermediates via increase in NOS2 expression is among the main IFN-γ-induced pathways involved in control of infections." (PMID 22666512, 2012). "Twenty-four hours after infection, strong upregulation was assayed in NOS2, Mapk11, CASP8 and Casp3 genes." (PMID 22280251, 2012). "IL-10 is an important anti-inflammatory cytokine produced by macrophages during infection that strongly inhibits IL-12 and NOS2 expression." (PMID 22829768, 2012). "Mice deficient for IFN-γ and for NOS2 are markedly susceptible to DENV-3 infection, with elevated lethality rates, more severe disease and increased viral load after infection." (PMID 22666512, 2012). "In the present study, NOS2 expression is increased during adapted DENV-3 infection in different targets organs of infection and this expression was controlled by IFN-γ." (PMID 22666512, 2012). "In accordance with these data, WT infected mice showed increased NOS2-positive staining in liver from day 5 after infection, peaking at day 7 after infection, virtually only in infiltrating leukocytes." (PMID 22666512, 2012). "Hamster arg2 mRNA was not expressed in the spleen throughout the course of infection, and hamster NOS2 mRNA was increased only slightly at day-56 of infection." (PMID 22275864, 2012). "Seventy-two hours after infection, Casp3 and NOS2 remained upregulated (4.4-fold and 7.7-fold, respectively, p < 0.001), while Mapk11 was no longer upregulated." (PMID 22280251, 2012). "In contrast, infection of unactivated macrophages typically leads to parasite survival and minimal levels of NOS2-dependent NO production, to the point that L. major was referred to as a “stealthy parasite”." (PMID 22523640, 2012). "It was interesting to find that the expression of nos2, which is responsible for macrophage production of NO, was significantly lower in the lungs of mice treated with CC-3052 at 21, 28 and 42 days post-infection." (PMID 21364878, 2011). "Evaluation of NOS2 staining in the liver by immunohistochemistry showed significant NOS2 expression, virtually only in infiltrating leukocytes, at day 7 after infection." (PMID 22206036, 2011). "We found that Mtb infection significantly increased the expression of tnf-α, 2.49/3.01; ifn-γ, 2.45/4.11; il-1β, 2.76/3.43; and nos2, 2.69/5.98 at 21 and 28 days post-infection respectively (differential expression ≥1.5 fold, P<0.05)." (PMID 21364878, 2011). "In contrast, CC-3052 treatment resulted in decreased gene expression: tnf-α, −1.63/−1.50; ifn-γ, −1.64/−1.54; il-1β, −1.67/−1.58; and nos2, −1.68/−1.84 at 21 and 28 days post-infection respectively." (PMID 21364878, 2011). "Compared to >50% of the cells expressing Arg1 at 48 after infection, only 2.5% of the cells were found to be NOS2+ by intracellular staining techniques." (PMID 21246055, 2011). "TNF-α, IL-1β and NOS2 are produced by macrophages in response to infection with Mtb, while IFN-γ is produced by dendritic cells and various lymphoid cells, including lymphoid cells of the innate immune response." (PMID 21364878, 2011). "This suggests that arginase competes with NOS2 to produce NO from arginine during the infection, leading to the suboptimal antibacterial effect of NOS2 in the B. pseudomallei-infected host." (PMID 21110886, 2010). "Immunohistochemical studies of the brain and immunoblot of brain lysates at 4 weeks post-infection revealed protein expression of NOS2 and TNF-α in both CD40−/− and control mice." (PMID 21217818, 2010).